TTYH3 (tweety family member 3)
Diseases named in the same sentence as TTYH3 in open-access papers (continued):
Sharing a sentence is not in itself a finding about the gene and the disease.
cancer (10 papers, 2019 to 2025). A tumor composed of atypical neoplastic, often pleomorphic cells that invade other tissues. "Given that TTYH3 encodes a chloride ion channel, multiple studies have highlighted the significant role of chloride ion channels in cancer progression." (PMID 38827027, 2024). "We further explored TTYH3 mutation through the IntOGen-Cancer Mutations Browser database, and the result also shown the mutation rate of TTYH3 is very low, and the mutations needle plot shown the distribution of the observed mutations along the protein sequence." (PMID 35844789, 2022). "However, little is known about the expression and function of TTYH3, a gene encoding a chloride ion channel, in cancer progression." (PMID 31652813, 2019). "Tweety homolog 3 (TTYH3) reportedly functions vitally in the development of diverse cancers, including NSCLC; nevertheless, its role in NSCLC metastasis remains ambiguous." (PMID 39930621, 2025). "Several previous studies have shown that TTYH3 is over expressed in cancer, indicating poor cancer prognosis." (PMID 37370118, 2023). "Cancer cell growth between control and TTYH3 knockdown cells for 3 days was compared using a cell counting assay." (PMID 36142409, 2022). "TTYH3 is a member of the calcium-activated chloride channel family and takes part in plentiful biological processes, particularly in cancer progression." (PMID 35935583, 2022). "The present findings also reveal the importance of TTYH3 expression and possible TTYH3-related pathways in cancer progression." (PMID 31652813, 2019). "We examined the differences of TTYH3 expression between cancers and their normal tissues using the Oncomine, UALCAN, and GEO (Gene Expression Omnibus) databases." (PMID 31652813, 2019). "Among the 33 cancer types, 16 displayed significantly higher TTYH3 expression levels compared to their normal counterparts and two cancers displayed lower TTHY3 expression levels." (PMID 31652813, 2019). "To explore the expression pattern of TTYH3 in various types of cancers, we examined the differences of TTYH3 expression between the cancers and their normal tissues using three independent bioinformatics databases." (PMID 31652813, 2019). "Co-alteration of TTYH3 and a group of the genes involved in the pathway of activation of the C3 and C5 complementary system implies a potential role of TTYH3 expression modulating cancer microenvironment." (PMID 31652813, 2019). "We further analyzed the expression of TTYH3 between 33 types of human cancer and their normal tissues with the expression data retrieved from combined TCGA and GTEx data using GEPIA tools." (PMID 31652813, 2019). "Here, we comprehensively analyzed the expression of TTYH3 and its clinical outcome in GC using publicly available cancer gene expression and patient survival data through various databases." (PMID 31652813, 2019). "This will help provide a full grasp of TTYH3's role in cancer progression." (PMID 38827027, 2024). "The expression of TTYH3 was compared in various cancer cell lines." (PMID 36142409, 2022). "The results indicated that TTYH3 may promote cancer progression by transporting calcium and chloride into cancer cells." (PMID 35844789, 2022). "The common overexpression of TTYH3 in cancers and its correlation with patient survival in HCC indicates that it may serve as a promising biomarker for predicting patient prognosis." (PMID 35844789, 2022). "We also examined the mechanism by which TTYH3 promoted cancer invasion and migration." (PMID 35844789, 2022). "As TTYH3 is involved in the Ca2+-activated chloride channel, we investigated whether Ca2+ or Cl- was involved in promoting cancer progression." (PMID 35844789, 2022).
cancer (continued). "Because of limited differential expression data, the TTYH3 downregulation pattern present in association with cancers is not easily identifiable (if present) for neurological disorders." (PMID 34262434, 2021). "Besides, the data retrieved from the Oncomine database or the results obtained from qRT-PCR, western blot, immunohistochemistry analyses, higher levels of TTYH3 were detected in OC specimens in comparison to non-cancer normal ovarian specimens." (PMID 34729116, 2021). "However, studies regarding TTYH3 have almost exclusively focused on its biochemical structure rather than prognosis prediction or its expression pattern in cancers." (PMID 34729116, 2021). "The data revealed the significantly increased expression of TTYH3 in various cancer types." (PMID 31652813, 2019). "Aside from this data, the impact of TTYH3 on the progress of cancer is unclear." (PMID 31652813, 2019). "To ascertain the ceRNA relationship between TTYH3 and HDAC7 in promoting cancer metastasis in vivo, we evaluated the effects of TTYH3‐3′UTR and HDAC7‐3′UTR on tumor cell colonization and dissemination by using nude mice hepatic metastasis models." (PMID 38827027, 2024). "Although TTYH3 has been identified as a gated chloride channel, its biochemical and subsequent biological functions have not been widely studied, especially in cancers." (PMID 35844789, 2022). "The analysis revealed downregulation of promoter methylation of TTYH3 in BLCA, irrespective of clinicopathological characteristics, such as individual cancer stage, race, sex, age, weight, smoking status, nodal metastasis status, and histological subtype (Figure A1)." (PMID 36142409, 2022).
tumor (7 papers, 2019 to 2025). "In our future research, we aim to delve deeper into unveiling the underlying mechanisms and potential tumor‐specific variations in the functionality of TTYH3." (PMID 38827027, 2024). "More recently, there has been an increasing number of studies on the role of TTYH3 in tumor progression." (PMID 38827027, 2024). "Subsequently, we analyzed the clinical stages of CRC patients in the Linkedomics database, TTYH3 was chosen as our research focus based on its remarkably higher expression in advanced‐stage tumor tissues." (PMID 38827027, 2024). "To investigate the mechanism of high TTYH3 expression in tumor tissue, we performed DNA methylation microarray with 850K BeadChip in seven paired HCC tissues." (PMID 35844789, 2022). "In conclusion, we identified TTYH3 regulates tumor development and progression via MK5/GSK3-β/β-catenin signaling in HCC and promotes itself expression in a positive feedback loop." (PMID 35844789, 2022). "Immunostaining showed that TTYH3 protein was highly expressed in the tumor cell membrane, and high TTYH3 protein expression was significantly correlated with poor DFS and OS in patient cohort from the Affiliated Hospital of Qingdao University." (PMID 35844789, 2022). "The results demonstrated that TTYH3 expression was higher in tumor than in normal tissues." (PMID 38827027, 2024). "We are uncertain whether the ion channel‐independent characteristics of TTYH3 are specific to CRC or exhibit tumor‐type specificity, as we have yet to explore this issue." (PMID 38827027, 2024). "Meanwhile, qRT-PCR detection showed significant upregulation of TTYH3 in BC tumor tissues." (PMID 35935583, 2022). "DNA hypomethylation in the tumor promoter may be one of the reasons for TTYH3 upregulation in HCC tissue." (PMID 35844789, 2022). "In terms of tumor grading, TTYH3 expression was significantly upregulated in all tumor grade." (PMID 31652813, 2019). "Furthermore, TTYH3 promoted tumor formation and metastasis in a mouse model." (PMID 35844789, 2022). "Here, we found that TTYH3 promoted NSCLC cell migration, invasion, EMT, and tumor metastasis." (PMID 39930621, 2025). "To investigate whether TTYH3 or HDAC7 participate in CRC angiogenesis, we established mice subcutaneous tumor models." (PMID 38827027, 2024). "Unlike previous findings on chloride channels in tumor progression, we found that TTYH3's migration‐promoting function on CRC cells is separate from its chloride channel activity." (PMID 38827027, 2024). "According to the Oncomine dataset, TTYH3 expression was higher in tumor tissue compared to that in nontumor tissue." (PMID 35844789, 2022). "The Ca2+ concentration was significantly higher in tumor tissue than in nontumor tissue (P < 0.01), and Ca2+ concentration was correlated with TTYH3 expression (P < 0.001, r = 0.4623)." (PMID 35844789, 2022).
infection (1 paper, 2024). The state of being infected such as from the introduction of a foreign agent such as serum, vaccine, antigenic substance or organism. "Genes that overlapped with control-biased OCRs (regions with reduced accessibility due to MVA infection) included IL1R1, LFNG, and TTYH3 genes, all of which were downregulated in MVA-infected cells." (PMID 38862613, 2024).
malignant carcinomas (1 paper, 2021). "To date, reports of TTYH3 in malignant carcinomas and the relationship with prognosis are limited." (PMID 34729116, 2021). "Moreover, up-regulated mRNA expression of TTYH3 was correlated with unfavorable OS in overall carcinoma stages while only predicted unfavorable PFS in stage III, and IV." (PMID 34729116, 2021).
TTYH3 also shares sentences with these, for which no sentence is quoted: amyotrophic lateral sclerosis (1 paper); brain cancer (1); cervical cancer (1); chronic myeloid leukemia (1); embryonal tumors (1); esophageal carcinoma (1); histiocytic sarcoma (1); kidney tumor (1); liver cancer (1); melanoma (1); non-small cell lung carcinoma (1); ovarian carcinoma (1); pancreatic cancer (1); sarcoma (1); small cell lung carcinoma (1); staphylococcus aureus infection (1); Streptococcus pneumoniae infection (1); thyroid carcinoma (1); toxoplasmosis (1); transitional cell carcinoma (1).